HIF1A (hypoxia inducible factor 1 subunit alpha)
Diseases named in the same sentence as HIF1A in open-access papers (continued):
Sharing a sentence is not in itself a finding about the gene and the disease.
tumor (continued). "Notably, HIF2α functions as an oncogene in ccRCC, whereas HIF1α may play a tumor-suppressive role, thereby illustrating the complexity of HIF signaling in this cancer type." (PMID 40725144, 2025). "Furthermore, the interaction between SMADs’ partners and HIF-1α favors metabolic reprogramming and tumor progression by benefiting PKM2 expression, an isoform prevalent in tumor cells, providing proliferating cells with differential control over glycolytic flux." (PMID 40943648, 2025). "Furthermore, macrophages sustainably produced oxygen to alleviate features associated with tumor hypoxic sites, inhibited HIF-1α expression in B16 cells, and enhanced the SDT efficacy of MChl-HP-NP, enabling T cell activation and reversing the tumor immune microenvironment." (PMID 40270890, 2025). "HIF-1α also drives the transcription of genes involved in glycolysis and glucose uptake, redirecting cellular metabolism toward lactate production, bypassing mitochondrial oxidative phosphorylation, thereby supporting tumor cells survival under low-oxygen conditions." (PMID 41009654, 2025). "In vivo experiments demonstrate that suppressing HIF-1α protein expression reduces the growth rate of subcutaneously formed tumors and decreases the expression levels of proteins associated with the P-PI3K/P-AKT, SOX2/OCT4, and MMP2/MMP9 pathways within the tumor." (PMID 39781344, 2025). "Additionally, SOX2 and OCT4 can synergize with HIF-1α to promote tumor cell migration and invasion." (PMID 39781344, 2025). "The correlation and findings in each of these studies suggest that HIF1α expression has a direct effect on the activation of angiogenesis and proliferation within the tumor environment and that the expression of a high amount of HIF1α is necessary to support continued tumor growth and survival." (PMID 40806669, 2025). "However, single-cell RNA sequencing in a human lymphoma cell model revealed that conditional deletion of HIF-1α in NK cells leads to slower tumor progression, increased expression of activation markers and effectors, and enrichment of the NF-κB pathway in tumor-infiltrating NK cells." (PMID 40297580, 2025). "Adding to this complexity, mutations in the VHL gene and the activation of the HIF-1α pathway play a crucial role in the development and progression of sporadic HBs, leading to the overexpression of pro-angiogenic factors like VEGF, which further exacerbates HBs tumor angiogenesis and growth." (PMID 40171270, 2025). "Additionally, tumors with stabilized HIF-1α often exhibit elevated local temperatures due to increased glycolytic activity and altered mitochondrial function, contributing to metabolic heat production in the tumor microenvironment." (PMID 40507237, 2025). "Therefore, we conducted a series of experiments to figure out whether the HBO treatment affects tumor chemotherapy sensitivity and proliferation by inhibiting HIF1α/HIF2α-ABCG2." (PMID 40370575, 2025). "Additionally, IF and flow cytometry results showed that overexpression of HIF-1α could counteract the effects of KynA, leading to increased lipid droplets accumulation in tumor cells." (PMID 39920992, 2025). "Tumor-specific PD-L1 could be induced by HIF-1α in certain circumstances." (PMID 38609977, 2024). "IL-6 can increase the activity of HIF-1α in tumor cells via STAT3 signaling, and HIF-1α may activate GLUT-1 via the Phosphatidylinositol-3-kinase (PI3K) pathway, which shifts glucose metabolism from oxidative phosphorylation to anaerobic processes (the Warburg effect)." (PMID 39963655, 2024). "Besides, HIF‐1α activation plays a pivotal part in in regulating tumor progression." (PMID 38217303, 2024). "Furthermore, HIF-1α and HIF-2α induce resistance to Sorafenib: after a prolonged period of administration, Sorafenib induces hypoxia in the tumor, leading to the expression of HIF-1α and NF-κB in a cellular clone more resistant to the hypoxic environment, thereby resistant to Sorafenib." (PMID 38927059, 2024).
tumor (continued). "Hypoxia‐inducible gene domain family member 1A (HIGD1A) is a HIF‐1α The regulated mitochondrial proteins can regulate oxygen consumption and reactive oxygen species production under hypoxic conditions, thereby activating the dormancy mechanism of tumor cells and enabling their survival." (PMID 37903487, 2024). "Similarly, ROS also increase HIF-1α activity for their tumor-promoting effect." (PMID 38880883, 2024). "Thus, we speculated that Scu may play a role in regulating tumor growth by reducing the stability of HIF1a." (PMID 38622131, 2024). "It has been demonstrated that hypoxia induces the binding of HIF-1α to the proximal promoter of zinc finger E-box binding homeobox 1 (ZEB1), which is highly expressed in cervical cancer hypoxic cells islets and is associated with a stronger pro-tumor phenotype." (PMID 38397187, 2024). "Therefore, we referred that the enhanced level of NREP may take a great part in BC tumor development, and this process may be related to HIF-1α." (PMID 38697993, 2024). "Moreover, CH has shown to inhibit hypoxia-driven progression of vasculogenic mimicry during angiogenesis, which is a common characteristic feature observed in tumour microenvironments by reducing the expression of HIF-1α, SPHK-1 and phospho-Akt/GSK-3β signaling in cancer cells." (PMID 38966181, 2024). "Therefore, we suspected that anlotinib could regulate tumor cell function by acting on HIF-1α, thereby affecting cell proliferation, angiogenesis, and survival." (PMID 38330738, 2024). "On the other hand, it may also lead to immunosuppression by inducing vascular damage and, consequently, blood perfusion, which in turn increases tumor hypoxia and the expression of HIF-1α, the pivotal transcription factor for maintaining oxygen balance and immunosuppression." (PMID 39698411, 2024). "In addition to the secretion of immunosuppressive factors and the infiltration of suppressive cells, the hypoxic environment of the TME itself induces the activation of the HIF-1α transcription factor, which plays a crucial role in the adaptation of tumor cells to the low-oxygen environment." (PMID 38893192, 2024). "However, TME-related HIF-1α activation promotes Tregs migration, leading to poor tumor prognosis." (PMID 38644503, 2024). "Radiation could ameliorate tumor hypoxia and reduces the transcription of HIF-1α." (PMID 38685050, 2024). "Targeting HIF-1α to inhibit tumor progression could serve as a new therapeutic target." (PMID 38542288, 2024). "Interestingly, areas staining for pAMPK and GLUT1 were abolished in echinomycin-treated tumours, which is consistent with the notion that HIF1α may activate AMPK and glycolysis independently." (PMID 38238426, 2024). "miR-20b-5p could modulate vascular endothelial growth factor A (VEGFA) transcription by targeting hypoxia-inducible 4 factor 1-alpha (HIF1α), may act as a tumor suppressor by hindering MMP-2 expression, leading to cell cycle arrest, and also has a regulatory function in oxygen balance." (PMID 39188680, 2024). "In this study, HIF-1α expression was more prominent in ICs compared with that in tumor cells, but it remains unclear whether this expression is induced by oxygen deficiency or in an oxygen-independent environment, namely, other pathogenic mechanisms of the malignant tumor." (PMID 39202223, 2024). "Furthermore, radiation improved tumor hypoxia to decrease HIF-1α dependent MIF secretion by NSCLC." (PMID 38685050, 2024). "Therefore, the HIF-1α-driven VEGF-signaling cascade is a critical driver of tumor angiogenesis." (PMID 38542288, 2024). "So, we assume that anlotinib may inhibit the tumor by regulating HIF-1α expression." (PMID 38330738, 2024). "However, blockade of the A2A adenosine receptor could abrogate the effects of HIF-1α in tumor cells, allowing leukemic cells to regain sensitivity to therapeutic agents." (PMID 37588219, 2024).
tumor (continued). "It was shown recently that, induced by hypoxia, HIF-1a protein expression in Tregs in the GBM TME is responsible for the active migration of Tregs to the tumor site; however, HIF-1a may inhibit the immunosuppressive function of Tregs by binding to FoxP3 protein." (PMID 38786032, 2024). "Moreover, hypoxia further enhanced the pro‐tumourigenic effect of neutrophils, that specific deletion of HIF‐1α in neutrophil could significantly reduce tumour burden accompanied by increase number and activity of antitumour immune cells." (PMID 39021279, 2024). "In addition, targeting hypoxia via VEGF or HIF-1α may need a deeper understanding of the cell-type or tumour expression profile." (PMID 38352889, 2024). "In conclusion, this study demonstrated that CS-siRNA/PEITC&L-cRGD NPs could effectively accumulate in tumor tissues, efficiently inhibit the accumulation of VEGF and HIF-1α expression, effectively curb tumor angiogenesis, block nutrient supply, and promote tumor apoptosis." (PMID 38584690, 2024). "Additionally, some antioxidants (e.g., ascorbate–vitamin C and N-acetyl cysteine) could be used to block tumor growth by inducing HIF-1α degradation." (PMID 38399410, 2024). "Furthermore, SETD7 methylation of HIF-1α inhibits angiogenesis and tumor growth." (PMID 39522095, 2024). "Moreover, HIF-1α cooperates with MYC to shape the tumor immune microenvironment." (PMID 38390324, 2024). "Future attempts could utilize engineered EVs to transport LW1564 into BC mitochondria because they can inhibit mitochondrial oxygen consumption, increase intracellular oxygen concentrations, stimulate HIF-1α degradation, and correct abnormal metabolism in tumor cells." (PMID 39434182, 2024). "Administration of the cardiacglycoside digoxin with the potential hypoxia-inducible factor 1-α(HIF1-α) and angiogenesis inhibitory effects could synergisticallyaugment mEHT-mediated tumor damage and reduce tissue hypoxia signalingand consequent vascular recovery in mEHT-treated TNBC tumors." (PMID 38357275, 2024). "Inspired by previous studies and our data showing that acetate supplementation could rescue IFN-γ production and tumor killing ability of Hif1α− / − T cells in vitro, we asked if this could act as an effective strategy to bypass ICB resistance in Hif1α− / − tumor-bearing mice in vivo." (PMID 39477954, 2024). "Moreover, it can play an anti-tumor role by blocking cell cycle G2/M and promoting apoptosis, which may be related to the decrease of HIF-1a expression." (PMID 38330738, 2024). "However, it has been suggested that HIF-1α may inhibit the proliferation of tumor cells by regulating the glutamine catabolic process." (PMID 38172980, 2024). "Moreover, it can play an anti-tumor role through blocking cell cycle G2/M and promoting apoptosis, which may be related to the decrease of HIF-1a expression." (PMID 38330738, 2024). "Moreover, in response to hypoxia, post‐RFA tumor cells could upregulate the HIF‐1α/vascular endothelial growth factor (VEGF) signaling pathway to promote angiogenesis in the remaining liver cancer tissues." (PMID 39359691, 2024). "Research indicates that HIF-1α may contribute to resistance against conventional therapies via various signaling pathways, including drug efflux, tumor stem cell enrichment, autophagy, and apoptosis, necessitating further investigation into HIF-1α-induced drug resistance mechanisms in BC." (PMID 38799423, 2024). "Moreover, the angiogenic switch regulated by HIF-1α is crucial for tumor growth and TME integrity." (PMID 38542288, 2024). "Additionally, the acetylation of lysine residue located in the oxygen-dependent degradation domain, performed by the arrest-defective-1 enzyme, is a modification recognized by the pVHL tumor suppressor, which is the second manner of tagging HIF-1α for ubiquitination." (PMID 39201656, 2024). "Thus, HIF-2α eventually predominates over HIF-1α in accelerating tumor progression in RCC." (PMID 39748950, 2024).
tumor (continued). "Therefore, vitamin C treatment could impair HIF1α activity and suppress tumor growth by enhancing HIF1 hydroxylase activity." (PMID 39564571, 2024). "Melatonin could inhibit tumor cell proliferation and migration by targeting HIF-1α and VEGF-A." (PMID 39204162, 2024). "Thus, the inhibition of HIF-1α unleashes NK cell anti-tumour activity and could be exploited for cancer therapy." (PMID 39508576, 2024). "Based on these findings, c-MYC and HIF-1α have been identified as potential therapeutic targets in colon cancer, which could theoretically lead to clinical trials targeting these factors to promote anti-tumor activity." (PMID 37450923, 2024). "Importantly, lncRNAs secreted by extracellular vesicles from tumor-associated macrophages (TAMs), HISLA, can reduce the hydroxylation and degradation of HIF-1α via blocking the interaction between PHD2 and HIF-1α, which promotes glycolysis and lactate accumulation in tumor cells." (PMID 39539540, 2024). "This review article examines the molecular mechanisms by which HIF-1α contributes to tumor progression, including its regulation by oxygen-dependent and independent pathways, interactions with oncogenic signaling networks, and impact on the tumor microenvironment." (PMID 39493156, 2024). "Indeed, a number of studies demonstrated that the enhanced tumor resistance to chemotherapy and aggressiveness relies on a mechanism involving the accumulation of the transcription factor HIF-1α in cancer cells where it promotes proliferation, migration and invasion." (PMID 38175205, 2024). "The novelty of the study includes the unravelling of the novel association of low miR-18a levels and the enrichment of hybrid E/M cells that leads to phenotypic changes including that of increased migration and stemness in a subgroup of ER-negative tumours that may be HIF-1α driven." (PMID 38786043, 2024). "Intratumoral hypoxia is a mechanism created through HIF-1α (hypoxia-induced factor-1α), which is known to induce tumor dedifferentiation, rapid growth, invasion, metastasis, angiogenesis, and resistance to chemotherapy, resulting in the formation of aggressive tumor morphology." (PMID 38922490, 2024). "Indeed, together with c-Myc, Hif-1α is known to simultaneously induce glycolytic genes and inhibitors of mitochondrial metabolism, to reduce mitochondrial biogenesis and to play a key role in metabolic reprogramming in many tumour types." (PMID 37198319, 2023). "It has been shown that in hypoxic environments, HIF-1α is considered a key protein that can effectively regulate the production of cytokines related to invasive metastasis and angiogenesis, which are essential for tumor cells to obtain sufficient oxygen and nutrients." (PMID 36976205, 2023). "Given our data showing that HIF-1α inhibition alleviates the tumor-promoting effect of GSTZ1 deficiency on HCC angiogenesis, we propose that a therapeutic strategy that suppresses SA-activated HIF-1α may improve current therapies that have limited effect on abnormal vasculature." (PMID 37906252, 2023). "HIF1A binds to the hypoxia response elements in the promoter region of target genes and is mainly involved in adaptive changes, enabling tumor cells to survive and proliferate in a hypoxic environment, thereby promoting malignant phenotypes and aggressive tumor behaviors." (PMID 36994412, 2023). "Therefore, this suggested that ESM1 and HIF-1α might have synergistic roles in tumor angiogenesis and cell proliferation, and they might promote CSCC progression through the VEGFα/VEGFR2/ERK signaling pathway." (PMID 37476182, 2023). "Hypoxia-inducible factor 1α (HIF-1α) is the main transcription factor involved in the adaptation to hypoxic environments in cancer cells, contributing to the regulation of metabolism, angiogenesis, cell survival, and drug resistance, thus making it an appealing target for tumor therapy." (PMID 37906252, 2023).
tumor (continued). "HIF-1α, a tumor growth signal that is upregulated during hypoxia, is responsible for activating the vascular endothelial growth factor pro-angiogenic gene, which has an effect on tumor growth, glucose metabolism, invasion, chemoradiotherapy resistance and prognosis." (PMID 36902423, 2023). "Therefore, inhibition of HIF1α target genes seems to be a better approach for anti-tumor therapy." (PMID 36982873, 2023). "Additionally, increased HIF-1α expression by tumor cells can decrease NK cell-mediated killing by downregulating tumor-derived MHC class I chain-related genes or by promoting the shedding of MICA, a ligand that triggers the cytolytic action of immune effectors, from the surface of tumor cells." (PMID 36980629, 2023). "In addition, various functional assays indicated that the attenuation of malignant tumor phenotype by Hsa_circ_0000566 knockdown was rescued by overexpression of HIF-1α, as indicated by the results of CCK-8, EdU, Transwell, colony formation, and apoptosis assays." (PMID 37008055, 2023). "In addition, a high level of HIF-1α after incomplete LITs also contributed to the elevated expression of HGF in the residual tumor, but HGF could in turn synergize with HIF-1α to promote tumor progression." (PMID 36831664, 2023). "In addition, it has been demonstrated that, in prostatic carcinoma cell lines, the hypoxic conditions of the tumor microenvironment trigger the expression of SUMO1/sentrin-specific peptidase 1 (SENP1) that in turn interacts with HIF1α to promote the Warburg effect and sustain cell proliferation." (PMID 36831534, 2023). "Moreover, tumor size was not related to high levels of HIF‐1α in IBC tissues (p = 0.461) but was associated with high OCN levels (p = 0.028)." (PMID 36971046, 2023). "Also, HIF-1α is a well-known regulator of glycolytic flux in tumor cells." (PMID 37965321, 2023). "High expression of HIF-1α may be a predictor of tumor radioresistance." (PMID 37296922, 2023). "Since a hypoxic tumour microenvironment is associated with late stages in CRC, we may conclude that sex differences in this case are underpinned by E2–GPER tumorigenic actions on HIF-1α/VEGF activation and on ATM suppression under hypoxia." (PMID 38137047, 2023). "Moreover, especially when incomplete, locoregional treatments can also induce immunosuppressive factors (such as IL-6, VEGF, HIF-1α, TGF-β, PD-1 and PD-L1), stimulate the accumulation of Tregs in the tumor and cause lymphopenia, leading to tumor progression in the end." (PMID 37239941, 2023). "Our in vitro data from glucose and lactose detection kits, CCK-8, RT-PCR and transwell assays further confirmed that EVE and HIF-1α inhibitor, 2-Methoxyestradiol (2ME2) inhibited the glucose uptake, lactic acid (LD) secretion, survival, polarization and pro-tumor migration function of TAMs." (PMID 37884960, 2023). "However, AU1 could hardly inhibit tumor progression in tumors derived from the HIF1α/HIF-2α DKO cells, suggesting that AU1 depends on HIF to exert the anti-tumor effect." (PMID 36967443, 2023). "Therefore, the HIF-1α mediated regulation of α-KG function under hypoxia may have a potential anti-tumour effect." (PMID 37108242, 2023). "In a study conducted on different cancer cell lines, it has been established that caveolin-1-dependent tumor suppression, especially in the absence of E-cadherin, is linked to reduced HIF1α transcriptional activity via diminished NOS-mediated HIF1α S-nitrosylation." (PMID 38067108, 2023). "It is suggested that lower expression of HIF1AN is correlated with a higher level of T cell exhaustion markers, which indicates that the tumor may under a hypoxia state, the HIF1A is activated, and the T cells enter a cellular state called “Exhaustion”, they unable to clear the tumor cells." (PMID 36816977, 2023). "Furthermore, the tumor immunosuppression was suggested to be induced by IL-6 via HIF1α activation." (PMID 36764954, 2023).